CASR (calcium sensing receptor)
Diseases named in the same sentence as CASR in open-access papers (continued):
Sharing a sentence is not in itself a finding about the gene and the disease.
coronary artery calcification (3 papers, 2014 to 2016). Calcification of the coronary artery, used as a measure of coronary atherosclerosis, a risk factor for myocardial infarction. "Univariate analysis of associations between CASR SNP genotypes and risk factors for aortic and coronary artery calcification." (PMID 25786244, 2015). "We investigated whether common CASR gene variants are predictors for aortic and coronary artery calcification or influence risk factors such as serum calcium, phosphate and glucose concentrations in RTRs." (PMID 25786244, 2015). "Comparison of CASR SNP genotypes in patients with low and high levels of aortic calcification (AoC) and coronary artery calcification (CAC)." (PMID 25786244, 2015). "This study demonstrates for the first time that total CaSR expression in human circulating monocytes is increased in RA patients with severe coronary artery calcification." (PMID 25134967, 2014). "First, with a cross-sectional design, a temporal relationship between total CaSR expression and coronary artery calcification cannot be proven." (PMID 25134967, 2014). "Nevertheless, the findings of this study indicate that the six common CASR polymorphisms are unlikely to play a major role in the development or progression of aortic or coronary artery calcification in patients with renal transplants." (PMID 25786244, 2015).
cyst (3 papers, 2018 to 2025). A sac-like closed membranous structure that may be empty or contain fluid or amorphous material. "Calcimimetics, the allosteric modulators of CaSR, slow late-stage cyst progression in ADPKD rat by enhancing the level of intracellular calcium." (PMID 33261193, 2020). "Together these data indicate that, besides reversing the principal dysregulations considered the most proximal events in ADPKD pathogenesis, selective CaSR activation in PKD1 deficient cells restores altered mitochondrial function that, in ADPKD, is known to facilitate cyst formation." (PMID 30197885, 2018). "The specific activation of CaSR elicited by its allosteric modulator, the calcimimetic R568, induced an increase in cytosolic Ca2+, a decrease in intracellular cAMP level and mTOR activity, and restored the altered mitochondrial function, all events known to promote cyst formation in ADPKD." (PMID 41465431, 2025).
Familial hypocalciuric hypercalcemia type 2 (3 papers, 2016 to 2017). "Gna11 is a calcium-sensing receptor, loss of function mutations of which cause familial hypocalciuric hypercalcemia type 2." (PMID 28859164, 2017).
Hyperglycemia (3 papers, 2013 to 2020). An increased concentration of glucose in the blood. "Meanwhile, we observed that hyperglycemia-associated apoptosis was inhibited when the CaSR was silenced." (PMID 23717692, 2013).
ischemia (3 papers, 2019 to 2021). A hypoperfusion of the BLOOD through an organ or tissue caused by a PATHOLOGIC CONSTRICTION or obstruction of its BLOOD VESSELS, or an absence of BLOOD CIRCULATION. "For example, the activation of CaSR exerts a protective function against endothelial injury in ischemia or reperfusion injury by inhibiting platelet activation." (PMID 33804544, 2021). "In summary, CaSR seems to play an important role in ischemia induced MI by influencing various cells and processes." (PMID 33804544, 2021). "Importantly, CaSR’s expression increases and its function evokes harmful effects in conditions of acute CNS damage entailing a subsequent neuroinflammation, such as ischemia/hypoxia/stroke and subarachnoid hemorrhage (which also causes an ischemia/hypoxia through local tissue compression)." (PMID 33261147, 2020). "In addition, CaSR inhibition by intra-cerebroventricular (ICV) injections of calcilytics effectively protected the hippocampal neurons of wild-type mice from ischemia-induced injury." (PMID 31336912, 2019). "Furthermore, it could be shown that the CaSR-activated neutrophils instigate cardiomyocyte apoptosis and thereby aggravate ischemia." (PMID 33804544, 2021).
kidney cancer (3 papers, 2016 to 2022). Primary or metastatic malignant neoplasm involving the kidney. "For example, CaSR overexpression in breast, lung, prostate and kidney cancers were positively correlated with tumor progression and shorter survival; inhibition or silence of CaSR markedly suppressed cancer cell proliferation, invasion, and migration." (PMID 36348350, 2022).
kidney failure (3 papers, 2016 to 2024). An acute or chronic condition that is characterized by the inability of the kidneys to adequately filter the blood. "Those previous results along with the present findings suggest that the effects of CaSR agonist might be limited to later or advanced stages of ADPKD, particularly in affected patients with kidney failure." (PMID 33976330, 2021).
magnesium deficiency (3 papers, 2020 to 2021). A nutritional condition produced by a deficiency of magnesium in the diet, characterized by anorexia, nausea, vomiting, lethargy, and weakness. "Magnesium deficiency has also been considered to be a potential cause of low PTH levels as magnesium participates in PTH secretion and action through interaction with the calcium sensing receptor." (PMID 32219087, 2020). "What this study adds: The CaSR mediates intestinal dipeptide absorption through the Ca2+/IKCa/hyperpolarization mechanism Clinical significance: CaSR‐PLC‐Ca2+‐IKCa pathway could be exploited as a potential target in human nutritional disorders." (PMID 31960592, 2020). "We reveal a novel CaSR‐PLC‐Ca2+‐IKCa pathway in the regulation of small intestinal dipeptide absorption, which may be exploited as a target for future drug development in human nutritional disorders." (PMID 31960592, 2020).
neuroblastic tumor (3 papers, 2013 to 2022). A group of nervous system tumors which display neuronal differentiation. "Association of CaSR gene polymorphisms and haplotypes with clinical and biological features of neuroblastic tumors." (PMID 23533647, 2013). "An evaluation of CaSR mRNA expression in primary neuroblastic tumors revealed that the receptor expression correlated with good prognostic variables, such as age at diagnosis <1 year, low clinical stage, low clinical risk, and differentiated histology." (PMID 31336912, 2019). "Overall and event-free survival of patients diagnosed with neuroblastic tumors according to CaSR genotypes." (PMID 23533647, 2013). "Overall and event-free survival of patients diagnosed with neuroblastic tumors according to CaSR haplotypes." (PMID 23533647, 2013). "In summary, our present data indicate that a tri-locus haplotype at the signal transduction region of the CaSR might be an independent predictor of outcome in patients diagnosed with neuroblastic tumors." (PMID 23533647, 2013).
orchitis (3 papers, 2020 to 2022). Inflammation of one or both testes due to viral or bacterial infections. "Overall, CaSR plays an important role in the proinflammatory process of UPEC-induced orchitis by promoting the secretion of IL-1β in TM." (PMID 33193351, 2020). "We find that CaSR promotes the secretion of proinflammatory factor IL-1β in the NLRP3 inflammatory corpuscle pathway in orchitis and that CaSR inhibitors reduce inflammatory damage to spermatogenic epithelial cells." (PMID 33193351, 2020). "Thus, we speculated that CaSR can activate NLRP3 inflammatory bodies in orchitis." (PMID 33193351, 2020). "However, the role of CaSR in UPEC-induced orchitis macrophages remains unclear." (PMID 33193351, 2020). "Su and co-workers developed a uropathogenic Escherichia coli (UPEC) rat orchitis model, through which they investigated the NLRP3 inflammatory pathway proteins in testicular macrophages, and in particular, the expression of CaSR (calcium-sensing receptor), responsible for the NLRP3 activation." (PMID 36289651, 2022). "Overall, elevated CaSR levels in TM in testes with UPEC-induced orchitis may impair testosterone synthesis through the activation of the NLRP3 pathway and PK2 is an upstream regulatory protein of CaSR." (PMID 33193351, 2020).
osteoarthritis (3 papers, 2013 to 2025). A noninflammatory degenerative joint disease occurring chiefly in older persons, characterized by degeneration of the articular cartilage, hypertrophy of bone at the margins and changes in the synovial membrane. "Additionally, CaSR contributes to subchondral bone metabolic dysregulation, with its hyperactivation exacerbating osteoarthritis progression through aberrant bone remodeling." (PMID 40860192, 2025). "CCR2, GPR4, α2A-AR, and CaSR will accelerate the progression of osteoarthritis." (PMID 40860192, 2025). "Collectively, PTH1R and CaSR represent opposing regulators in osteoarthritis: PTH1R exerts protective effects via bone-cartilage crosstalk, while CaSR drives pathological differentiation and matrix breakdown, highlighting their therapeutic potential as targets for osteoarthritis management." (PMID 40860192, 2025). "In addition, CaSR expression was found to be upregulated in the synovial lining layer in RA patients compared to osteoarthritis samples." (PMID 32843625, 2020).
pituitary adenomas (3 papers, 2021 to 2025). "This indicates that targeting CaSR expression could be beneficial in reducing proliferation in neuroendocrine tumours, such as corticotrophinomas that represent up to 10% of all surgically removed pituitary adenomas, however, this remains to be tested in detail." (PMID 34223822, 2021).
Renal cyst (3 papers, 2018 to 2025). A fluid filled sac in the kidney. "In PKD, the activation of CaSR results in the reduction of cAMP levels and subsequent inhibition of renal cyst growth." (PMID 33261193, 2020). "We show here that CaSR activation had a positive effect also on mTOR activity, which is upregulated in cystic kidney epithelial cells showing altered cell proliferation." (PMID 29632324, 2018).
squamous cell carcinoma (3 papers, 2015 to 2022). A carcinoma arising from squamous epithelial cells. "Our data indicate that in the human, CaSR is present in normal esophageal tissue as well as in esophageal adenocarcinoma, squamous cell carcinoma, Barrett’s and eosinophilic esophagitis." (PMID 26603452, 2015). "In conclusion, CaSR is expressed in normal esophagus as well as in Barrett’s, esophageal adenocarcinoma, squamous cell carcinoma, and eosinophilic esophagitis." (PMID 26603452, 2015). "Esophageal tissues from patients diagnosed with eosinophilic esophagitis, adenocarcinoma, squamous cell carcinoma, or Barrett’s esophagus, all showed strong positive staining for CaSR." (PMID 26603452, 2015). "At first sight, the findings of photoprotective effects of CaSR knockdown or pharmacologic inhibition in human keratinocytes are inconsistent with reports that mice with epidermal double knockout of the VDR and CaSR spontaneously develop squamous cell carcinomas." (PMID 35288938, 2022). "Our study demonstrated that CaSR is expressed in the esophagus of normal human subjects as well as in esophageal tissues from patients suffering from different pathological conditions of the esophagus like eosinophilic esophagitis, Barrett’s esophagus, adenocarcinoma, and squamous cell carcinoma." (PMID 26603452, 2015).
thyroid cancer (3 papers, 2016 to 2025). "The presence of a novel CASR mutation with thyroid cancer in this case is of unknown significance and can only be resolved in long-term follow-up and future studies." (PMID 41311753, 2025). "In contrast to thyroid carcinoma cells, CaSR-integrin actions mediating migration of GCPs during cerebellar development appears to be mediated not by phospholipase C, but rather by the ERK and Akt signaling." (PMID 27303307, 2016). "Pharmacological stimulation of the CaSR using the positive allosteric modulator NPS R-568 potently enhanced thyroid carcinoma cell adhesion and migration." (PMID 27303307, 2016). "In thyroid carcinoma cells, the CaSR together with integrins facilitate cellular migration." (PMID 27303307, 2016). "CaSR/integrin protein complexes have been identified in thyroid carcinoma cells and in cerebellar granule cells, and may exist in other tissues and cells." (PMID 27303307, 2016). "In addition to thyroid carcinoma cells and cerebellar granule neurons, the question arises as to what other cells and tissues might utilize the CaSR/integrin system?" (PMID 27303307, 2016).
Acquired hypocalciuric hypercalcemia (2 papers, 2016 to 2022). "Acquired hypocalciuric hypercalcemia (AHH) is a rare disease caused by calcium-sensing receptor (CaSR) autoantibodies, to date, showing either simple blocking or biased properties (i.e., stimulatory or blocking effects on different downstream signaling pathways)." (PMID 36099030, 2022). "However, CASR mutations are only detected in ≤70% of FHH and ADH cases, referred to as FHH type 1 and ADH type 1, respectively, and studies in other FHH and ADH kindreds have revealed these disorders to be genetically heterogeneous." (PMID 27647839, 2016).
amyloidosis (2 papers, 2016 to 2020). A disorder characterized by the localized or diffuse accumulation of amyloid protein in various anatomic sites. "It is also worth mentioning here that the CaSR PAM (calcimimetic) NPS R-568 administration intensified the release of Aβ42-os from the NAHAs further confirming the noxious role of Aβ•CaSR signaling in AD amyloidosis." (PMID 33261147, 2020).
ankylosis (2 papers, 2020 to 2021). Fixation and immobility of a joint. "Targeting CaSR may be a novel potential therapeutic strategy to slow down the progression of axial structural ankylosis." (PMID 33259138, 2020). "Yet, the study did not examine if non-osteoblast CaSR expression contributes to ankylosis and how flux in extracellular Ca2+ levels at inflamed entheses may alter CaSR activity to influence bone remodeling." (PMID 34095174, 2021).
Anorexia (2 papers, 2022). Lack of desire to eat (loss of appetite). "Subsequently, we demonstrated that DON elicited brain-gut peptide-driven anorexia and emesis in a murine anorexia model and mink emesis model by activating the Calcium-sensing receptor (CaSR) and a transient receptor potential (TRP) channel named TRP ankyrin 1 (TRPA1), respectively." (PMID 35737032, 2022). "Our previous studies have demonstrated that the activations of CaSR and TRP channels are involved in DON-induced anorexia and emesis induction." (PMID 35737050, 2022). "This is in accordance with our previous research that DON selectively activated CaSR and elevated hormones CCK and PYY3–36 to mediate anorexia." (PMID 35737050, 2022).
Anxiety (2 papers, 2020 to 2025). Intense feelings of nervousness, tension, or panic often arise in response to interpersonal stresses. "SNS treatment normalized depression/anxiety behaviors, restored CaSR expression and ameliorated synaptic damage." (PMID 40469980, 2025). "Our in vivo study clearly demonstrated that Tojapride effectively ameliorated modified RE rat anxiety‐related behaviour, prevented reflux of gastric and duodenal contents, diminished the pathological impairment and inhibited the proinflammatory pathway of the CaSR/NLRP3 inflammasome." (PMID 31859410, 2020).
atopic dermatitis (2 papers, 2025). "The activation of calcium, CaSR, and the PLC/PI3K/PKC/Akt signaling pathways would be effectively modulated by agents for the treatment of chronic wounds and differentiation-defective skin conditions, such as psoriasis or atopic dermatitis." (PMID 40298779, 2025).
autosomal dominant hypoparathyroidism (2 papers, 2010 to 2025). "A single case had been previously reported in which a variant in CaSR, Leu616Val, was associated with autosomal dominant hypoparathyroidism and short stature." (PMID 39658204, 2025).
bone tumors (2 papers, 2018 to 2025). "Both PTH1R and CaSR participate in the bone-tumor vicious cycle and influence the skeletal metastatic niche." (PMID 30151009, 2018).
brain injury (2 papers, 2016 to 2022). Acute and chronic (see also brain INJURIES, CHRONIC) injuries to the brain, including the cerebral hemispheres, CEREBELLUM, and brain STEM. "The calcium-sensing receptor (CaSR) plays a key role in activating NLRP3-mediated signaling cascades (e.g., NOD-like receptor signaling pathway) related to the occurrence of cardiovascular diseases and ischemic brain injury under hypoxic conditions." (PMID 36077479, 2022).
cataract (2 papers, 2017 to 2023). Partial or complete opacity of the crystalline lens of one or both eyes that decreases visual acuity and eventually results in blindness. "Cataracts have also been reported as part of various ectopic calcifications in a mouse model of activating CASR mutation." (PMID 36812896, 2023).
Cerebral ischemia (2 papers, 2016). Restriction of arterial blood supply to the brain associated with insufficient oxygenation to support the metabolic requirements of the tissue. "Intriguingly, CaSR antagonists were shown to reduce CaSR expression levels, brain tissue loss and neurological deficits, in animal models of traumatic brain injury and cerebral ischemia." (PMID 27065884, 2016).
chronic thromboembolic pulmonary hypertension (2 papers, 2015 to 2016). Chronic thromboembolic pulmonary hypertension (CTEPH) is characterized by the persistence of thromboemboli in the form of organized tissue obstructing the pulmonary arteries. "Here, we found that the blockade of CaSR by calcilytics attenuated excessive cell proliferation in IPAH-PASMCs, but did not affect it in PASMCs from normal subjects and patients with chronic thromboembolic pulmonary hypertension (CTEPH)." (PMID 26375676, 2015).
Cirrhosis (2 papers, 2023 to 2024). A chronic disorder of the liver in which liver tissue becomes scarred and is partially replaced by regenerative nodules and fibrotic tissue resulting in loss of liver function. "In cirrhosis, CaSR reduces intrahepatic resistance to portal flow." (PMID 38920679, 2024). "The negative correlation between the severity of fibrosis/cirrhosis and 25-hydroxy-vitamin D levels could also be due to the fact that vitamin D, through the activation (VDR) and Calcium-sensing receptor (CaSR), imparts portal hypotensive effect as evident from a study in a rat model." (PMID 36672644, 2023).
colorectal adenocarcinoma (2 papers, 2014 to 2015). The most common type of colorectal carcinoma. "In the present study we show that CaSR expression negatively correlates with proliferation markers, but positively correlates with differentiation and apoptosis markers in samples from human colorectal adenocarcinomas." (PMID 25701758, 2015).
COVID-19 (2 papers, 2022 to 2024). A disease caused by infection with severe acute respiratory syndrome coronavirus 2. "In addition, upon viral infection, the CaSR could also be upregulated in immune cells and eventually may exacerbate the inflammatory response in severely ill COVID-19 patients." (PMID 36467702, 2022). "Interestingly, we observed the elevation of soluble/shed CaSR in the plasma of acute COVID-19 patients, which was not the case in LC patients." (PMID 38304426, 2024).
cryopyrin-associated periodic syndrome (2 papers, 2020 to 2023). Cryopyrin associated periodic syndrome (CAPS) defines a group of autoinflammatory diseases, characterized by recurrent episodes of systemic inflammatory attacks in the absence of infection or autoimmune disease. "Increased extracellular Ca2+ concentrations trigger activation of the NLRP3 inflammasome in monocytes through Ca2+-sensing receptor (CaSR) which causes inflammation in human cryopyrin-associated periodic syndrome (CAPS)." (PMID 36195671, 2023).
depression (2 papers, 2020 to 2025). "And SNS treatment normalised CaSR protein expression levels in stressed rats brain, indicating the important role of CaSR in SNS to improve depression." (PMID 40469980, 2025). "To clarify whether depression-like behavior and CaSR are correlated, we analyzed the correlation between CaSR levels and depression-like behaviors." (PMID 40469980, 2025).